H4C1 (H4 clustered histone 1)
Description:
Core component of nucleosome. Nucleosomes wrap and compact DNA into chromatin, limiting DNA accessibility to the cellular machineries which require DNA as a template. Histones thereby play a central role in transcription regulation, DNA repair, DNA replication and chromosomal stability. DNA accessibility is regulated via a complex set of post-translational modifications of histones, also called histone code, and nucleosome remodeling.
Synonyms: H4FA; HIST1H4A
Target class: Other nuclear protein
Gene: Protein-coding gene on chromosome 6 (26,021,649 to 26,022,847, forward strand). Ensembl gene ENSG00000278637.
Subcellular location: Nucleus; Chromosome
Pathways (Reactome):
Gene expression (Transcription): B-WICH complex positively regulates rRNA expression; DNA methylation; ERCC6 (CSB) and EHMT2 (G9a) positively regulate rRNA expression; MLL4 and MLL3 complexes regulate expression of PPARG target genes in adipogenesis and hepatic steatosis; NoRC negatively regulates rRNA expression; PRC2 methylates histones and DNA; RNA Polymerase I Promoter Escape; RNA Polymerase I Promoter Opening; RUNX1 regulates genes involved in megakaryocyte differentiation and platelet function; RUNX1 regulates transcription of genes involved in differentiation of HSCs; Regulation of endogenous retroelements by KRAB-ZFP proteins; Regulation of endogenous retroelements by Piwi-interacting RNAs (piRNAs); Regulation of endogenous retroelements by the Human Silencing Hub (HUSH) complex; SIRT1 negatively regulates rRNA expression; Transcriptional regulation by small RNAs
Chromatin organization: CHD1 and CHD2 subfamily; CHD6, CHD7, CHD8, CHD9 subfamily; ChAHP complex assembly; HATs acetylate histones; HDACs deacetylate histones; HDMs demethylate histones; Interaction of NuRD complexes with transcription factors; NuRD complex assembly; PKMTs methylate histone lysines; RMTs methylate histone arginines
DNA Repair: Cleavage of the damaged purine; Cleavage of the damaged pyrimidine; Nonhomologous End-Joining (NHEJ); Processing of DNA double-strand break ends; Recognition and association of DNA glycosylase with site containing an affected purine; Recognition and association of DNA glycosylase with site containing an affected pyrimidine; Recruitment and ATM-mediated phosphorylation of repair and signaling proteins at DNA double strand breaks
Cell Cycle: Condensation of Prophase Chromosomes; Deposition of new CENPA-containing nucleosomes at the centromere; G2/M DNA damage checkpoint; Inhibition of DNA recombination at telomere; Packaging Of Telomere Ends
Developmental Biology: Activation of anterior HOX genes in hindbrain development during early embryogenesis; Chromatin modifications during the maternal to zygotic transition (MZT); Replacement of protamines by nucleosomes in the male pronucleus
and 20 more pathways
Gene Ontology:
Molecular function: protein binding; RNA binding; structural constituent of chromatin; DNA binding; protein heterodimerization activity
Biological process: negative regulation of megakaryocyte differentiation; nucleosome assembly; chromatin organization; protein localization to CENP-A containing chromatin; telomere organization
Cellular component: CENP-A containing nucleosome; chromosome, telomeric region; extracellular exosome; membrane; nucleoplasm; nucleosome; nucleus; protein-containing complex; extracellular region; chromosome
Genetic constraint (gnomAD): Loss-of-function variants: 9 observed, 4.65 expected, observed/expected ratio (o/e) 1.94, 90% interval 1.01 to 1.96. That is too few expected variants to judge how well the gene tolerates losing a copy. Missense variants: 124 observed, 161.52 expected, observed/expected ratio (o/e) 0.77, 90% interval 0.66 to 0.89. Synonymous variants: 74 observed, 55.64 expected, observed/expected ratio (o/e) 1.33, 90% interval 1.1 to 1.61.
Homologues: Orthologues: chimpanzee H4C6 (100% identical), zebrafish H4C1 (100% identical). Paralogues in human: H4C11 (100% identical), H4C12 (100% identical), H4C13 (100% identical), H4C14 (100% identical), H4C15 (100% identical), H4C16 (100% identical), H4C2 (100% identical), H4C3 (100% identical), H4C4 (100% identical), H4C5 (100% identical), H4C6 (100% identical), H4C8 (100% identical), and 2 more.
Diseases named in the same sentence as H4C1 in open-access papers:
H4C1 is named in the same sentence as 8 diseases in open-access papers, as found by Europe PMC text mining. Sharing a sentence is not in itself a finding about the gene and the disease. The quoted sentences say what the papers report.
breast carcinoma (1 paper, 2021). "H2BC4 and H4C1 are also overexpressed in breast cancer and the first is overexpressed in its metastatic relapse." (PMID 33662042, 2021).
lupus (1 paper, 2025). "Autoreactivity against H4C1, a histone and recognized target of autoreactivity in drug-induced lupus, increased on-treatment exclusively in patients who developed toxicity." (PMID 40449958, 2025).
steatosis (1 paper, 2025). Increased lipid within the cytoplasm of cells. "Specifically, H4C1, OIT3, ANPEP, CCDC25 and KLHL41 were identified as potential biomarkers for steatosis, GP1BA as a candidate marker for MASH and C7, IGHD and GNB1 as potential biomarkers for fibrosis severity." (PMID 41301514, 2025).
endocrine system disorder (1 paper, 2021). A disease involving the endocrine system. "Network 1 (IPA® score 67) was annotated to endocrine system disorders, gastrointestinal disease, and immunological disease, and identified H4 clustered histone 1 (H4C1), histone h3, and E3 ubiquitin-protein ligase (RBX1) as nodes with the highest number of network connections." (PMID 34845190, 2021).
tumor (1 paper, 2024). "Notably, H4C1, EGFR, and ITGB1 maintained their prominence in terms of presentation levels across subpopulations stratified by HPV status and tumor stage." (PMID 39136024, 2024).
H4C1 also shares sentences with these, for which no sentence is quoted: gastrointestinal disease (1 paper); melanoma (1); meningioma (1).